KDR (kinase insert domain receptor)
Diseases named in the same sentence as KDR in open-access papers (continued):
Sharing a sentence is not in itself a finding about the gene and the disease.
cancer (1,618 papers, 2001 to 2026). A tumor composed of atypical neoplastic, often pleomorphic cells that invade other tissues. "KDR gene mutations, insertions, and deletions are associated with cancer occurrence, and alterations are observed in 3.02% of all cancers including lung adenocarcinoma, melanoma, colon adenocarcinoma, and conventional glioblastoma." (PMID 37803932, 2023). "METTL1 expression was positively correlated with PVRL2 in nearly all cancers, whereas, it was negatively associated with KDR and CD274 in nearly all cancers." (PMID 35432338, 2022). "Herein, we found 14 genes with UTR variants, of which four cancer-associated genes harbor variants in 3′ UTR (KDR and CARD11) and 5′ UTR (CSMD3 and TLX3)." (PMID 35884575, 2022). "KDR: Kinase insert domain receptor (KDR) is a primary vascular endothelial growth factor receptor that encodes a crucial receptor regulating the cancer angiogenesis/metastasis switch." (PMID 32560530, 2020). "ANLN has been identified as an interactor with KDR that encodes a key receptor mediating the cancer angiogenesis/metastasis switch." (PMID 32560530, 2020). "KDR is commonly mutated across cancer types, and is one of the primary targets of the multi-targeted TKIs, with up to eighty percent of activity being inhibited by TKIs." (PMID 29383146, 2017). "The IntOGen cancer drivers, dbSNP, and ClinVar databases were used to exclude commonly reported germline mutations (such as the recurrent mutations in KDR gene) and FFPE false-positive mutations." (PMID 28978153, 2017). "Among these, five novel mutations in cancer-related genes (KDR, STK11, MLH1, KRAS, and PTPN11) were detected in ES, and these mutations were confirmed with traditional Sanger sequencing." (PMID 27077911, 2016). "KDR/VEGFR2 gene, which encodes VEGFR2 tyrosine kinase, is involved in neovascularization to promote the supplementation of nutrients and oxygen for the proliferation of cancer cells." (PMID 37341071, 2023). "The genetic variations of KDR may influence its systemic production and its effects on vascular endothelial cells in cancer patients, consequently causing individual differences in the responses of patients treated with therapies targeting KDR." (PMID 19435508, 2009). "Thus, 3D185 could maximize the therapeutic potential against the targets FGFR and CSF-1R in cancer patients and avoid the classic toxic effects associated with KDR." (PMID 31438996, 2019). "PPARα agonists also decreased the PPARα/Sp1-dependent expression of KDR and Cyp7b1 and induced pl6NK4a in non-cancer cell lines." (PMID 39858066, 2025). "The top 13 GDF6-related target genes (such as VEGFA, FLT1, and KDR) showed positive correlations with the tissue expression in various cancer types, suggesting a conserved regulatory network." (PMID 40699648, 2025). "The KDR gene—identified as a top cancer-related target interacting with acetaminophen targets—encodes one of the two receptors for VEGF, a major growth factor for endothelial cells." (PMID 41516250, 2025). "PDGrapher can also suggest potential anti-cancer therapeutic targets: it highlighted KDR as a top-predicted target for non-small cell lung cancer (see heading PDGrapher predicts therapeutic targets across cancer types in the Methods section)." (PMID 38260532, 2025). "The expression of PTGS2 and KDR was significantly higher in stage 3 and stage 4 cancer, respectively." (PMID 38426619, 2024). "We labeled cell types as endothelial cell (Endothelial, gene expression of PLVAP, KDR, PTPRB) and cancer associated fibroblasts cell (CAFs, gene expression of FAP, MMP11, PDGFRB, SFRP2, PDGFRA, ADAMTS2)." (PMID 37065499, 2023).
cancer (continued). "Cancer researchers have established that KDR is an important clinical biomarker and a key drug target in numerous solid tumors." (PMID 38178861, 2023). "Correlations were observed between CREB3L1 expression and several immune biomarkers such as CD28, CXCR4 and KDR in several cancers." (PMID 36171879, 2022). "Multiple studies have indicated that inhibition of KDR leads to G2/M phase arrest in cancer cells as well as in endothelial cells." (PMID 35273218, 2022). "As a result, 14 genes were found to be regulated by miRNAs (miRabel score ≤ 0.05), four of which are cancer-associated genes (CARD11, CSMD3, KDR, and TLX3)." (PMID 35884575, 2022). "On the other hand, KDR (Kinase insert domain-containing receptor), ranked 24th, was reported to play a critical role in the metastasis of cancer and is used as a molecular target in cancer therapy." (PMID 35831792, 2022). "Up-regulation of KDR by periostin (POSTN) induces angiogenesis which was an important step in the development of cancer." (PMID 35057823, 2022). "KDR, SH2D2A, SRC, and KRAS were included in the VEGF signaling pathway, of which variants were associated with cancer recurrence when they were assessed simultaneously." (PMID 34599262, 2021). "Next, we identified prognostic gene mutations (ATR, ERBB3, KDR, and MUC6), fusions (GOPC-ROS1 and NTRK1-SH2D2A), and VEGF signaling pathway associated with cancer recurrence." (PMID 34599262, 2021). "According to the analysis of the TGCA-HNSC dataset, VEGFR2 (also known as KDR) expression was increased in cancer tissue compared with that in normal tissue." (PMID 34459788, 2021). "Among these 22 is the gene KDR, whose gene product VEGFR2 is a prominent cancer target with anti-VEGFR2 drugs on the market for over a decade." (PMID 32459810, 2020). "As a result, the interaction of VEGF with Flt-1 (VEGFR-1) and KDR (VEGFR-2) receptors on the surface of the endothelial cells is inhibited, which leads to the reduction of vascularization and inhibition of cancer growth." (PMID 31547532, 2019). "In our assays, the RTKs EGFR and KDR, both abundantly found as oncogenes in various other cancer types, robustly triggered notochord hyperplasia." (PMID 31221659, 2019). "The epigenetic silencing of KDR should be considered in the activation of the VEGF-VEGFR signaling pathway in the cancer cells." (PMID 26949191, 2016). "All of the target compounds were evaluated the activity against four cancer cell lines and VEGFR2/KDR kinase." (PMID 26512636, 2015). "Some studies have shown that KDR is expressed strongly in the cytoplasm and nuclei of both cancer cells and peritumoral vessels." (PMID 19435508, 2009). "Kinase insert domain-containing receptor (KDR) plays a critical role in the metastasis of cancer and is used as a molecular target in cancer therapy." (PMID 19435508, 2009). "Strikingly, ACACA expression exhibited significant negative correlations with the immune checkpoint-related genes (PDCD1, LAG3, LAGLS9, IDO1, CD244, CTLA4 and TIGIT), while showing positive associations with other genes (TGFBR1, KDR, IL10RB, CD160 and CD274) across most cancer types." (PMID 41169354, 2025). "Notably, several small-molecule inhibitors and monoclonal antibodies targeting KDR are already approved by the FDA for cancer therapy." (PMID 38918393, 2024). "For example, the stromal subset consisted of endothelial cells identified by expressions of VWF, PECAM1 and KDR, pericytes with high RGS5, ACTA2, and COL4A1 expressions, and cancer-associated fibroblasts (CAFs) identified by significant expressions of COL1A1, DCN and LUM." (PMID 38925650, 2024).
cancer (continued). "Of the kinase inhibitor gene targets evaluated, high pre-treatment PIKFYVE, KDR, NTRK1, IKBKB, FLT1, or FGFR1 expression was each associated with lower odds of achieving CR when controlling for cancer type, biopsy site, age at the time of treatment initiation, and ICB agent." (PMID 38464258, 2024). "KDR overexpression has been studied in relation to several different types of cancer, including lung, colon, uterine and ovarian, and breast cancers." (PMID 37114147, 2023). "Moreover, significantly elevated levels of KDR mRNA have been reported in malignant tumor endothelia." (PMID 37114147, 2023). "Although different subgroups of ccRCC were not studied here, significant differences were found in the angiogenesis-related genes FLT1, FLT4, and KDR between cancer and benign EVs as well as ccRCC EVs and pRCC EVs, which fits more with a lower aggressive ccA phenotype." (PMID 34331598, 2021). "Recently, alterations in the KDR (VEGFR2) gene have been reported for some human cancers." (PMID 29067211, 2017). "However, FLT1 (normal, 1.3 %; cancer tissue, 4.4 %; p = 0.023) and KDR (2.2 % vs. 16.4 %; p = 0.008) methylations were significantly higher in cancer tissues, compared to normal tissues." (PMID 26380584, 2015). "As KDR is a molecular target of cancer therapy, our clinical and KDR expression data may help to improve lung cancer therapy targeted to KDR." (PMID 19435508, 2009). "Although a precise reason for why this relationship should exist is unknown, some studies have established a more aggressive phenotype in cancers that have lower expression of KDR." (PMID 16780590, 2006). "Additionally, four cancer-associated genes (CARD11, CSMD3, KDR, and TLX3) carried untranslated regions (UTRs) variants, which may impact gene regulation by affecting the miRNAs hybridization regions." (PMID 35884575, 2022). "For example, dysregulated vascular endothelial growth factor signaling from damaging variants in the kinase insert domain receptor (KDR) gene, which encodes a vascular endothelial growth factor receptor, could account for malformations of the great vessels and cancer-associated angiogenesis." (PMID 33084842, 2021). "Interestingly, KDR, besides the 10-fold overexpression in the cancer cells from the PDGFRA#4 and #6 cases with gene amplification, showed mild to moderate overexpression without gene amplification, with a 7.7-fold upper range, in the majority of cases from many subgroups." (PMID 34572759, 2021). "Moreover, we identified four novel candidate cancer-associated genes (CTCF, ARHGAP35, NF1, and KDR) which may be crucial in the carcinogenesis of EEC." (PMID 30886832, 2019). "Therefore, the potential success or failure of anti-VEGF/VEGFR drugs in cancer cells originating from different tissue types and with different levels of FLT1 or KDR methylation remains unclear." (PMID 26380584, 2015). "However, the clear role of individual KDR SNPs and their physiological functions in cancer progression and prognosis remains unknown." (PMID 24599305, 2014). "Hence, specific inhibitors of KDR tyrosine kinase are thought to be useful in treating cancer." (PMID 19435508, 2009). "VEGFA ligand expressed on epithelial cells (cancer cells and AT1 cells) communicated with FLT1 (VEGF receptor 1), KDR (VEGF receptor 2), and NRP1 (a coreceptor for KDR) expressed on ECs99." (PMID 39803458, 2025). "Merck’s angiogenic signature was selected as genes co-expressed with known angiogenic genes, KDR, TIE1, TEK, and CD34, in public pan-cancer genomic datasets." (PMID 39835481, 2025). "KDR (also known as VEGFR2), which exhibits a high affinity for VEGF, is significantly upregulated in cancer cells and activated ECs within the TME, driving proangiogenic processes." (PMID 39770505, 2024).
cancer (continued). "The correlation analysis of 24 immunosuppressants indicated that EDNRA was positively correlated with ADORA2A, CSF1R, KDR, TGFB1, and TGFBR1 in cancers, including BLCA, CHOL, ESCA, READ, and STAD." (PMID 39601333, 2024). "Our analysis indicated a positive correlation between B3GNT5 and immune activation markers, including CD276, PVR, NT5E, STING1, and TNF-SF18, as well as immunosuppressive genes TGF-ΒR1, IL-10PR, KDR, CD274, PDCD1LG2, IL-10, and IDO1 in the pan-cancer cohort." (PMID 39671359, 2024). "The “Proteoglycans in cancer” pathway was also exclusively enriched in AA-SScL fibroblasts, driven by the upregulation of IGF2, DCN, LUM, COL1A1, COL1A2, and the receptors KDR and TLR4." (PMID 36835058, 2023). "For FAP, significantly positive Pearson correlations coefficients for most cancer entities were found with prominent angiogenesis-related genes FLT1 (also known as VEGFR1), KDR (also known as VEGFR2), HIF1A, and ETS1." (PMID 36672341, 2023). "Among newly identified genes, eleven other cancer targets were detected: MPL; ERBB4; VHL; FGFR3; KIT; KDR; PTEN; KRAS; PTPN11; ERBB2; and SMARCB1." (PMID 35621644, 2022). "Cabozantinib is an orally administered, RTK inhibitor of multiple kinases effecting cancer cell growth, angiogenesis, and metabolism including MET, VEGFR2/KDR, AXL, TIE2, RET, and KIT." (PMID 36969746, 2022). "In vitro studies reveal that selpercatinib selectively inhibits both wild-type and altered RET, spares KDR/VEGFR2 activity, and selectively targets RET-altered cancer cells." (PMID 35957881, 2022). "Although several studies determined the direct or indirect network between PIK3CA, KDR, GAB1, VEGFA, PLCG, and CRKL and hsa-miR-429 in various cancers, the functional regulation of these genes in Bag-1 deficiency conditions is still needed to elucidate." (PMID 37533517, 2022). "The increased expression of KDR and FLT1 complex in cancer cells and macrophages was correlated with upregulated VEGFA signaling in cancer cells in solid areas, suggesting upregulated angiogenesis and vascular reconstitution." (PMID 35874770, 2022). "According to our results, SYK, KDR, and FLT1 levels in cancer tissues were 3.7 times, 1.7 times and 1.3 times higher than those in normal tissues, respectively." (PMID 35435107, 2022). "BR55 is targeted against the kinase insert domain receptor (KDR), the human analog of vascular endothelial growth factor type 2, VEGFR2, which is well documented for its vasculature overexpression in various cancer types." (PMID 33532585, 2021). "With the success of the first and, to date, only targeted-MB in clinical trials for various cancers, BR55 (kinase insert domain receptor-targeted peptide), a rapid expansion of targeted US contrast agents is expected." (PMID 34845270, 2021). "KDR (VEGFR-2) is overexpressed in many solid tumors and has been established as an important clinical biomarker and a key drug target in cancer research." (PMID 32028264, 2020). "Both mouse (SVR) and human (PAE/KDR) VEGFR2 positive endothelial cells bound targeted MBs and thMBs at significantly higher levels (p < 0.0001, two-way repeated measure ANOVA) than SW480 CRC cancer cells which showed minimal binding of MBs." (PMID 33042265, 2020). "The vascular endothelial growth 2 (VEGFR-2), also known as (KDR) has spurted as an attractive pharmacological target in cancer therapy pertaining to its crucial rule in tumorangiogenesis." (PMID 31852269, 2019). "FLT1, a tyrosine kinase receptor, acts as a promoter in cancer growth and metastasis, whose affinity with VEGFA is approximately ten times higher than KDR." (PMID 31383782, 2019).
cancer (continued). "In line with previous observations, genes involved in cancer development were represented on Bs of four studied species: red fox (KIT), Chinese raccoon dog (ENPP1, GNAS, HMGCR, KDR, RET), brocket deer (BCL6, RASA1, RET), and Korean field mouse (JAK3)." (PMID 30103445, 2018). "Of the four top hits, KDR and PTPN11 were included in screening 1,001 cancer cell lines in the Genomics in Drug Sensitivity in Cancer database." (PMID 29383146, 2017). "Herein, we report the newly synthesized target compounds and their biological activities against four cancer cell lines A549, Hela, MCF-7, PC-3, and VEGFR2/KDR kinase." (PMID 26512636, 2015). "Studies in different cancers have suggested that several downstream proangiogenic growth factors can be increased by COX-2, like VEGF and Flt-1, Flk-1/KDR, angiopoietin-1, tie-2, MMP2, and OPN." (PMID 24191167, 2013). "In human, this focal event contains a fragile site (FRA4B) and the well-known cancer genes PDGFR, KIT and KDR, which are also in the fish focal gain." (PMID 24009526, 2013). "Some cancer cells express one of the two VEGF receptors, VEGFR-1 or VEGFR-2 (Flk/KDR), and can be stimulated by VEGF signaling." (PMID 22949815, 2012). "PPARƔ/Sp1 interactions were also involved in decreased fatty acid synthesis; induction of adipocyte triglyceride lipase (Atgl); induction of acetyl-CoA synthetase (AACS); and decreased follistatin, KDR, angiotensin type 1 receptor (AT1R) and the thromboxane receptor in non-cancer cell lines." (PMID 39858066, 2025). "Also, in most of the cancers, there was a significant correlation between UBE2C gene expression and CD96, CD274, CSF1R, KDR, and PDCD1LG2." (PMID 38577722, 2024). "Additionally, genes such as VEGFA on chromosome 12, and KDR and KIT on chromosome 13, are frequently amplified in these cancers." (PMID 39872607, 2024). "ENST00000311534 was significantly correlated with HMGB1, ENST00000326094 was significantly correlated with BTN3A1, CD160, TGFBR1, and IL6R, and ENST00000375991 was significantly correlated with CD276, ENTPD1, HMGB1, TLR4, KDR, and TGFBR1 among these 33 immune genes in more than 20 cancer types." (PMID 39766805, 2024). "Furthermore, RBFOX2 expression showed a significant association with immunosuppressive genes like PD-L1, CTLA4, VTCN1, KDR, and TGFBR1 across different types of cancers." (PMID 38881877, 2024). "Among them, VEGF-VEGFR2 (also known as the kinase insert domain-containing receptor, KDR, or fetal liver kinase-1, Flk-1) binding in cancer cells stimulates the secretion of MMPs, leading to ECM degradation and providing a pathway for cells to invade nearby tissues." (PMID 36358584, 2022). "In addition, the results uncovered that the expression of ADAM17 was positively correlated with an immunostimulator (IL6R) and immunoinhibitors (CD274, KDR, TGFBR1) in most cancer types." (PMID 35720350, 2022). "KDR expression has been detected in a wide variety of cancer cells and vascular endothelial cells but not in normal cells." (PMID 33381459, 2020). "That is, by transiting triple negative cancer cells to a less malignant state via concomitantly modulating ANLN and KDR gene expression, we could obtain desired clinical results using the same strategy as that for luminal cancers." (PMID 31636652, 2019). "On the contrary, EPHB2, ERBB4, FGFR1, PDGFRA, KDR, and FLT1 genes showed deletion in cancer cells." (PMID 32038722, 2019). "We noticed that, although identified independently, several of these aberration hubs were connected together through protein-protein interactions and formed a protein network that included several known cancer driver factors such as MYC, EGFR, PIK3C2B, CDK1, and KDR." (PMID 29861861, 2018). "However, in some cancer cells, changes in intracellular VEGF-VEGFR signaling occur due to epigenetic gene silencing of FLT1 and KDR." (PMID 26380584, 2015).